RRM1 (ribonucleotide reductase catalytic subunit M1)
Description:
Provides the precursors necessary for DNA synthesis. Catalyzes the biosynthesis of deoxyribonucleotides from the corresponding ribonucleotides.
Synonyms: RR1; PEOB6; R1; RIR1
Tractability: Small molecule: an approved drug acts on it; a structure with a bound ligand is known; it has a high-quality binding pocket; it belongs to a druggable protein family. PROTAC: ubiquitination databases record sites on it; its protein half-life has been measured; a small molecule that binds it is known.
Target class: Enzyme; Oxidoreductase
Safety:
Unwanted effects reported when the protein is acted on. In parentheses: how it was acted on, where the effect was seen, and who reports it.
nausea (source: ClinPGx)
neutropenia (source: ClinPGx)
progression-free survival (source: ClinPGx)
Gene: Protein-coding gene on chromosome 11 (4,094,707 to 4,138,932, forward strand). Ensembl gene ENSG00000167325.
Subcellular location: Cytoplasm
Subcellular location (Human Protein Atlas): Cytosol; Basal body; Centriolar satellite; Plasma membrane
Pathways (Reactome):
Metabolism: Interconversion of nucleotide di- and triphosphates
Gene Ontology:
Molecular function: identical protein binding; protein binding; ribonucleoside-diphosphate reductase activity; ATP binding; ribonucleoside-diphosphate reductase activity, thioredoxin disulfide as acceptor; disordered domain specific binding; purine nucleotide binding; ribonucleoside-diphosphate reductase activity, glutaredoxin disulfide as acceptor
Biological process: 2'-deoxyribonucleotide biosynthetic process; DNA repair; mitochondrial DNA replication; positive regulation of G0 to G1 transition; positive regulation of G1/S transition of mitotic cell cycle; positive regulation of G2/M transition of mitotic cell cycle; ribonucleoside diphosphate metabolic process; deoxyribonucleotide biosynthetic process; DNA synthesis involved in DNA repair; dTMP biosynthetic process; protein heterotetramerization
Cellular component: cytosol; ribonucleoside-diphosphate reductase complex; cytoplasm; mitochondrion
Genetic constraint (gnomAD): Loss-of-function variants: 8 observed, 59.76 expected, observed/expected ratio (o/e) 0.13, 90% interval 0.078 to 0.24. The upper end of that interval is the gene's LOEUF score, 0.24, which puts it in group 1 of 6, group 1 being the genes least tolerant of losing a copy. Missense variants: 332 observed, 697.14 expected, observed/expected ratio (o/e) 0.48, 90% interval 0.43 to 0.52. Synonymous variants: 218 observed, 237.78 expected, observed/expected ratio (o/e) 0.92, 90% interval 0.82 to 1.03.
Homologues: Orthologues: chimpanzee RRM1 (99% identical), macaque RRM1 (99% identical), dog RRM1 (98% identical), pig RRM1 (98% identical), guinea pig RRM1 (98% identical), mouse Rrm1 (98% identical), rat Rrm1 (96% identical), rabbit RRM1 (92% identical), zebrafish rrm1 (91% identical), tropical clawed frog rrm1 (90% identical), Drosophila melanogaster RnrL (75% identical), Caenorhabditis elegans rnr-1 (73% identical).
Diseases named in the same sentence as RRM1 in open-access papers:
RRM1 is named in the same sentence as 109 diseases in open-access papers, as found by Europe PMC text mining. Sharing a sentence is not in itself a finding about the gene and the disease. The quoted sentences say what the papers report.
lung cancer (38 papers, 2007 to 2026). A malignant neoplasm involving the lung. "Some of the pyrimidine metabolic rate–limiting enzymes, such as TK1, UCK2, and RRM1, were reported to be associated with the poor outcomes of lung cancer in systematic review or meta-analysis." (PMID 32638267, 2020). "In summary, to the best of our knowledge, this is the first study to systematically identify the relationship between the tagSNPs of RRM1 and individual susceptibility to lung cancer." (PMID 27335251, 2016). "Compared with the T/T and A/T genotype of RRM1 *151A>T, the A/A genotype had an increased risk for overall lung cancer (adjusted OR, 1.33)." (PMID 27335251, 2016). "We used logistic regression analysis to examine potential associations between polymorphisms in the RRM1 genes and the risk of lung cancer after adjusting for age, gender, and lifestyles." (PMID 27335251, 2016). "Compared with the T/T and A/T genotypes of RRM1 *151A>T, the A/A genotype had an increased risk for overall lung cancer (adjusted OR, 1.33; 95% CI, 1.11–1.60) by recessive models." (PMID 27335251, 2016). "In summary, this is the first study to systematically identify the relationship between the polymorphisms of RRM1 and individual susceptibility to lung cancer." (PMID 27335251, 2016). "While the T/T+G/T genotypes of RRM1 ‐585T>G behaved as protective factors to increase the susceptibility to lung cancer (adjusted OR 0.44, as compared with the C/C genotype)." (PMID 27335251, 2016). "While the T/T+G/T genotypes of RRM1 ‐585T>G behaved as protective factors in increasing the susceptibility of lung cancer (adjusted OR, 0.44; 95% CI, 0.24–0.84) as compared with the C/C genotype." (PMID 27335251, 2016). "In the recessive model, RRM1 *151A>T had a remarkable association with the susceptibility of lung cancer with 1.43 (95% CI, 1.17–1.74; P = 0.00)." (PMID 27335251, 2016). "It is anticipated that the RRM1 *151A>T, RRM1 ‐756T>C, and RRM1 ‐585T>G polymorphisms will improve the predictive prognosis of lung cancer sensitivity." (PMID 27335251, 2016). "In studies with lung cancer cell lines, RRM1 overexpression is associated with resistance to gemcitabine therapy." (PMID 24647522, 2014). "Additionally, the T/T+T/C genotypes of RRM1 ‐756T>C were risk factors that increased the susceptibility to lung cancer (adjusted OR 1.54, as compared with the C/C genotype)." (PMID 27335251, 2016). "Additionally, the T/T+T/C genotypes of RRM1 ‐756T>C behaved as risk factor of enhanced susceptibility of lung cancer (adjusted OR 1.54; 95% CI, 1.10–2.15) as compared with the C/C genotype." (PMID 27335251, 2016). "Finally, we identified three common polymorphisms of RRM1 that were associated with lung cancer in the Chinese population." (PMID 27335251, 2016). "The expression of RRM1 in lung cancer tissues was generally lower than that in adjacent tissues, while an opposite trend was observed in breast cancer." (PMID 38274374, 2024). "Overexpression of RRM1 has been observed in lung cancers, sarcoma, and central nervous system cancers." (PMID 36713030, 2023). "Compared to the lung cancer or malignant mesothelioma cell lines, bladder cancer cells showed significantly higher RRM1 gene expression (96.7 ± 8.1% vs. 47.2 ± 10.2%, p < 0.005)." (PMID 33921102, 2021). "The normalized RRM1 gene expression ratio was evaluated in nine human bladder cancer, six lung cancer, and six malignant mesothelioma cells." (PMID 33921102, 2021). "The genes tested were TBP as a housekeeping gene, EGFR, ERCC1 and RRM1 as genes with potential predictive roles for lung cancer therapy, and HIF1 as a gene regulated by hypoxia, at least partially on RNA level." (PMID 30947297, 2019). "To further characterize the expression pattern of RRM1, RRM2, and RRM2B in different pathological types and stages of cancer, we chosen lung cancer as a representative cancer type as it is the leading cause of cancer death all over the world." (PMID 31637211, 2019).
lung cancer (continued). "Since lung cancers are derived from different cell types and carcinogenesis of different subtypes of lung cancer may be initiated by diverse DNA damage insults, the risk related to the RRM1 polymorphisms was further evaluated among non–small‐cell lung cancer (NSCLC) and SCLC." (PMID 27335251, 2016). "We detected six tag SNPs of RRM1 genotypes in a cohort of 1007 patients with primary lung cancer and 1007 age‐ and sex‐matched population controls using SNaPshot detection technology." (PMID 27335251, 2016). "Hopefully, the RRM1 *151A>T, RRM1 ‐756T>C, and RRM1 ‐585T>G will improve the prediction of lung cancer sensitivity." (PMID 27335251, 2016). "Immunohistochemical analyses of 187 early-stage lung cancer tumor specimens revealed a statistically significant co-expression of RRM1 and Bmi1." (PMID 24614341, 2014). "We describe the RRM1, RNF2, and Bmi1 interaction and co-localization, the mechanisms by which RNF2 and Bmi1 regulate RRM1 levels and cellular response to gemcitabine, and in situ protein levels in tumor specimens derived from patients with lung cancer." (PMID 24614341, 2014). "siRNA-mediated down-regulation of RRM1 sensitizes lung cancer cells to gemcitabine treatment in vivo and in vitro." (PMID 23922955, 2013). "RRM1 mostly increased in the sections from bladder, cervical, colorectal, head and neck, liver and lung cancers, as well as melanoma and sarcoma." (PMID 23922955, 2013). "RRM1 is involved in carcinogenesis, tumor progression, and the response of non–small-cell lung cancer to treatment." (PMID 24023754, 2013). "In earlier study, it suggested continuous exposure of lung cancer cell lines to increasing amounts of gemcitabine resulted in increased expression of RRM1." (PMID 22439756, 2012). "However, RRM1 was also reported to have an inhibitory effect on the occurrence, invasion, and metastasis of lung cancer." (PMID 36713030, 2023). "Similarly, the Kaplan-Meier survival analysis showed that pyrimidine metabolic rate–limiting enzymes DTYMK, NT5C3, RRM1, RRM2, TK1, TYMS, and UCK2 were all associated with adverse prognosis in the lung cancer." (PMID 32638267, 2020). "However, the direction of effect was not consistent with the study by Bepler and colleagues showing RRM1 expression as a predictor of good outcome for patients with lung cancer." (PMID 30458017, 2018). "In addition, clinical studies have shown that high levels of RRM1 or RRM2 are associated with a poor prognosis in both pancreatic and lung cancers." (PMID 28797284, 2017). "Recent studies have shown that RRM1 expression can be a powerful predictor of survival or chemotherapy sensitivity in patients presenting with carcinomas who are treated with adjuvant gemcitabine‐based chemotherapy including lung cancer." (PMID 27335251, 2016). "It has been reported that high expression levels of ERCC1 and RRM1 may reduce the response rate and survival rate in lung cancer patients treated with cisplatin and/or gemcitabine." (PMID 27800005, 2016). "In addition, PTBP1 can also play a pro‐lung cancer role by regulating the stability of mRNA of downstream target genes, and PTBP1 can promote the progression of lung cancer through the binding of RRM1 to AXL mRNA, resulting in its unstable regulation of AXL expression." (PMID 40579921, 2025). "The biological function of RRM1 in lung cancer is controversial and may require further research." (PMID 34188151, 2021). "However, the relationship between the ribonucleotide reductase M1 (RRM1) gene and susceptibility to lung cancer has not been well addressed." (PMID 27335251, 2016). "Moreover, RRM1 is a metastasis suppressor gene through PTEN‐regulated pathways in lung cancer." (PMID 27335251, 2016). "However, the relationship between the single nucleotide polymorphisms (SNP) of RRM1 and the susceptibility of lung cancer to chemotherapy has not been well addressed." (PMID 27335251, 2016).
lung cancer (continued). "However, there are reports, including a prospectively conducted phase III clinical trial, of RRM1 either not being significantly associated or possibly oppositely associated with survival in lung cancer patients receiving a gemcitabine-containing regimen." (PMID 24215511, 2013). "In addition, another research showed reduced RRM1 expression increased sensitivity to gemcitabine in lung cancer cell lines, and found RRM1 expression in tumor is a major predictor of disease response to gemcitabine chemotherapy during a prospective phaseII clinical trial with NSCLC." (PMID 22439756, 2012). "And the pyrimidine metabolic rate–limiting enzymes DTYMK, NT5C3, RRM1, RRM2, TK1, TYMS, and UCK2 had particular values in lung cancer prognosis." (PMID 32638267, 2020). "However, whether the polymorphism of RRM1 was related to individual risk of developing lung cancer has not been well investigated." (PMID 27335251, 2016). "Immunohistochemistry for RRM1 and RRM2 was performed on a lung cancer tissue microarray (TMA) and analyzed." (PMID 26001082, 2015). "First, we compared the expression of six molecular biomarkers (MDR-1, LRP, RRM-1, EGFR, ERCC-1, and BRCA-1) in the primary lung carcinoma and the metastatic lymph nodes of patients with the two subtypes of NSCLC." (PMID 22890830, 2012). "Ribonucleotide reductase subunits M1 (RRM1) and M2 (RRM2) are involved in the metabolism of gemcitabine (2′,2′-difluorodeoxycytidine), which is used for the treatment of nonsmall cell lung cancer." (PMID 18414411, 2008). "RNA interference-mediated depletion of RRM1, the catalytic subunit of ribonucleotide reductase (RNR), or pharmacological inhibition of RNR significantly potentiated inhibition of lung cancer cell clonogenic survival in vitro and xenograft growth in vivo by DAC treatment." (PMID 41748545, 2026). "In contrast, no study showed down-regulated expression of RRM1 (0 of 19) or RRM2 (0 of 19) in all subtypes of lung cancer, 22.2% (2 in 9) of the Oncomine studies demonstrated a down-regulated RRM2B expression in cases of LUSC and LCLC." (PMID 31637211, 2019). "However, RRM1 also acts as a tumor suppressor gene that inhibits tumor cell growth and metastasis by inducing the expression of the tumor suppressor gene PTEN in lung cancer." (PMID 28797284, 2017). "RRM1 and ERCC1 overexpression has been extensively investigated as potential predictive markers of tumor sensitivity to conventional chemotherapy agents, most thoroughly in lung cancer." (PMID 22436573, 2012). "Based on the observations that RNR was one of the afatinib-targeted proteins, we then further examined whether there was a combination effect of afatinib with gemcitabine (a well-known inhibitor of RNR) on the viability, RRM1 and RRM2 protein levels of human lung cancer cells." (PMID 29765556, 2018). "The previous study of PRR11 was conducted and interpreted in the setting of lung cancer and showed that PRR11-knockdown dysregulated the expression of multiple important gene in critical pathways such as cell cycle, tumorigenesis and metastasis (e.g. CCNA1, RRM1, MAP4K4 and EPB41L3)." (PMID 26252227, 2015). "Recent studies of Asian and Western patients have firmly established that lipoprotein receptor-related protein-1, ribonucleotide reductase M1 (RRM-1), EGFR, and excision repair cross-complementing gene 1 (ERCC-1) may be useful molecular markers to guide drug selection in patients with lung cancer." (PMID 22890830, 2012). "Silencing of Rrm1 and Rrm2 markedly enhanced the cytotoxicity of the topoisomerase I inhibitor camptothecin that might be exploited in chemotherapeutic strategies and RRM2 was shown to regulate Bcl-2 in lung cancers and considered to be a worthy target in cancer therapy." (PMID 27602772, 2016).
lung cancer (continued). "In addition, low/negative RRM1 mRNA and protein levels have been reported to correlate significantly with higher response rate and a better prognosis in lung cancer patients treated with gemcitabine-based chemotherapy, and in pancreatic and biliary cancer patients treated with gemcitabine alone." (PMID 24215511, 2013).
pancreatic cancer (35 papers, 2007 to 2025). "In summary, we demonstrated that RRM1 expression is significantly associated with poorer postoperative prognosis of pancreatic cancer patients." (PMID 34111175, 2021). "In the present study, we provide evidence that aberrant RRM1 expression is associated with poorer postoperative prognosis in pancreatic cancer." (PMID 34111175, 2021). "In pancreatic cancer patients treated with gemcitabine, RRM1 levels inversely correlate with OS where high expression of RRM1 is associated with poor survival, suggesting an important role for RRM1 in intrinsic resistance to gemcitabine." (PMID 29144412, 2017). "In contrast, high expression of RRM1 was associated with poor survival after gemcitabine treatment in patients with recurrent pancreatic cancer." (PMID 23710668, 2013). "Meanwhile, RRM1 expression has been shown to be a powerful predictor of survival or chemotherapy susceptibility in patients with carcinomas, such as pancreatic cancer 23, advanced nasopharyngeal carcinoma 24, and gastric cancer 25, treated with adjuvant gemcitabine‐based chemotherapy." (PMID 27335251, 2016). "In this study, we established various gemcitabine-resistant subclones of human pancreatic cancer cell lines, and investigated changes in gene expression associated with gemcitabine transport and metabolism, that is, hENT1, dCK, RRM1, and RRM2 mRNA, in the development of gemcitabine resistance." (PMID 17224927, 2007). "TCGA-PAAD analysis showed that FOXP1 and RRM1, which is a well-established marker upregulated in GR pancreatic cancer, have a significantly strong positive correlation." (PMID 40169859, 2025). "Western blot analysis and qRT-PCR results confirmed that the expressions of hENT and dCK were upregulated and that the expression of RRM1 was downregulated in pancreatic cancer cells withNCOA6 knockdown." (PMID 40065720, 2025). "Both SLC38A5 and RRM1 mRNA levels were higher in gemcitabine-resistant pancreatic cancer tissues than in gemcitabine-sensitive patient tissues." (PMID 37887353, 2023). "RRM1 was reported to accumulate at the DNA damage sites and facilitate damage repairment which helps pancreatic cancer cells to overcome the apoptosis induced by gemcitabine." (PMID 36211828, 2022). "In another research, expression of the other miRNA (miR-101-3p) was down-regulated in pancreatic cancer, which targeted RRM1 to reverse gemcitabine resistance in the cancer." (PMID 35043728, 2022). "Our immunohistochemical analysis indicated the clinical importance of high RRM1 expression in gemcitabine chemoresistance against pancreatic cancer consistent with reported evidence." (PMID 34111175, 2021). "We focused on the location of RRM1 expression in pancreatic cancer cells and found that it was mainly present in the cytoplasm, as shown by immunofluorescence and immunohistochemical staining." (PMID 34111175, 2021). "First, RRM1 expression in pancreatic cancer tissues of 121 patients who underwent surgical resection was determined by immunohistochemical staining." (PMID 34111175, 2021). "The notable finding from the present study is that RRM1 expression affects postoperative prognosis on adjuvant treatment in pancreatic cancer patients." (PMID 34111175, 2021). "Patients with pancreatic cancers expressing high levels of RRM1 had poorer OS following adjuvant chemotherapy." (PMID 34111175, 2021). "In the present study, we examined RRM1 expression and determined its clinical and biological significance in pancreatic cancers." (PMID 34111175, 2021). "We quantified RRM1 in four established human pancreatic cancer cell lines (Hs766T, MIAPaCa2, PSN1, and Panc1)." (PMID 34111175, 2021). "In our model of gemcitabine exposure of pancreatic cancer cells, drug-induced DNA damage activated RRM1 expression in the cytoplasm." (PMID 34111175, 2021). "RRM1 inhibition with specific siRNA or hydroxyurea enhanced the cytotoxic effects of gemcitabine for pancreatic cancer cells." (PMID 34111175, 2021).